XRCC1 (X-ray repair cross complementing 1)
Diseases named in the same sentence as XRCC1 in open-access papers (continued):
Sharing a sentence is not in itself a finding about the gene and the disease.
cancer (continued). "Analysis of available epidemiological literature on cancer incidence and its associations with alterations in DNA repair pathways support the involvement of BER, and in particular XRCC1, in cancer risk." (PMID 25800737, 2015). "While the development of PARP inhibitors (discussed in next section) removes some incentive to therapeutically target XRCC1, this protein clearly represents an important predictive factor for cancer risk and platinum-based therapeutics in PDA." (PMID 25988138, 2015). "So far, most epidemiological research concerning XRCC1 has been focusing on the prevalence of polymorphisms, and possible links to cancer risk for carriers of certain polymorphic traits." (PMID 25800737, 2015). "There have been studies regarding the XRCC1 Arg280His polymorphism and other cancers in different populations." (PMID 25927275, 2015). "Taken together, these results suggest that XRCC1 knockdown causes pathway changes that correlate strongly with a ‘cancer blueprint’." (PMID 25800737, 2015). "Only a few studies have investigated the association between the XRCC1 280His allele and risk of cancer." (PMID 26271249, 2015). "Stratification analyses of age, tobacco smoking, alcohol drinking and family history of cancer with XRCC1 194 (Arg>Trp) polymorphism are shown in Table-III." (PMID 26101477, 2015). "In a recent pre-clinical study, we have demonstrated that ATM, DNA-PKcs and ATR inhibitors are synthetically lethal in XRCC1 deficient cancer cells." (PMID 26674120, 2014). "An increasing number of reports have shown a correlation between single nucleotide polymorphism (SNP) of the XRCC1 gene and the risk to develop various cancers, including AML." (PMID 25074383, 2014). "Pooled analysis of the interaction effects between PARP1 Val762Ala and XRCC1 Arg399Gln on overall cancer risk." (PMID 24853559, 2014). "To provide evidence that such an approach is feasible, we have recently shown that XRCC1-deficient cancer cells are sensitive to ATM, DNA-PKcs, and ATR inhibitors." (PMID 25111287, 2014). "The joint effect between PARP-1 Val762Ala and XRCC1 Arg399Gln genotypes on the risk of cancer was addressed in the present study." (PMID 24853559, 2014). "Literature data suggest a protective role of the Trp/Trp genotype of the Arg/Trp polymorphism of the XRCC1 gene against the development of cancer, and this function can be underlined by increasing the activity of BER." (PMID 24402573, 2014). "XRCC1 Arg399Gln has been reported to be significantly associated with risks of gastric, lung, and colorectal cancers." (PMID 24497981, 2014). "Although more than 200 single nucleotide polymorphisms (SNPs) have been identified in XRCC1, only three common SNPs have been widely investigated in cancer risk." (PMID 24497981, 2014). "There is evidence that some of the XRCC1 polymorphisms found in cancer cells correlate with defects in the repair of DNA damage induced by several anti-cancer agents." (PMID 25074383, 2014). "Previous studies have demonstrated that the XRCC1 Arg194Trp gene polymorphism is associated with the susceptibility to esophageal, gastric, lung, breast and other types of cancer." (PMID 25202399, 2014). "In the XRCC1 gene, a functional polymorphism, Arg399Gln (rs25487) has been extensively investigated in many cancers." (PMID 24489692, 2014). "Several studies have suggested the effect of a possible interaction between XRCC1 polymorphisms and environmental factors on cancer risk." (PMID 23383237, 2013). "We also examined the association of the XRCC1 Arg399Gln polymorphism and cancer risk according to cancer type and source of controls." (PMID 24205095, 2013). "We further examined the association of the XRCC1 Arg399Gln polymorphism and cancer risk according to cancer type and ethnicity because there was significant heterogeneity between studies." (PMID 24205095, 2013). "First, CHO cells as well human cancer cells deficient in XRCC1 were highly sensitive to ATR inhibitors." (PMID 23451157, 2013).
cancer (continued). "The Arg399Gln polymorphism in the X-ray cross-complementing group 1 (XRCC1) had been implicated in cancer susceptibility." (PMID 24205095, 2013). "Overall, our results show that XRCC1 Arg399Gln polymorphism is associated with increased cancer risk when all eligible studies were pooled into the meta-analysis." (PMID 24205095, 2013). "To derive a more precise estimation of the association between the XRCC1 Arg399Gln polymorphism and overall cancer risk, we performed a meta-analysis of 297 case-control studies, in which a total of 93,941 cases and 121,480 controls were included." (PMID 24205095, 2013). "Actually, several studies demonstrated the effect of gene-gene interactions between XRCC1 polymorphisms and other genes in DNA repair pathway on cancer risk." (PMID 23717668, 2013). "Nonsynonymous XRCC1 polymorphisms Arg399Gln, Arg194Trp, and Arg280His have been implicated in the risk of various cancers." (PMID 24363792, 2013). "XRCC1 Arg399Gln was reported to be associated with susceptibility and prognosis of various cancers.The rs1801133 (C667T) variant is a common polymorphism of the MTHFR gene that leads to an amino acid substitution and decreased enzyme activity." (PMID 24340057, 2013). "And a meta-analysis also suggested that XRCC1 Arg194Trp polymorphism is a cancer susceptible factor among Chinese." (PMID 23704969, 2013). "In the past decade, a number of molecular epidemiological studies have been done to evaluate the association between XRCC1 Arg399Gln polymorphism and different types of cancer risk in diverse populations." (PMID 24205095, 2013). "The previous published data on the association between XRCC1 Arg399Gln polymorphism and cancer risk remained controversial." (PMID 24205095, 2013). "Based on biochemical properties described for XRCC1 polymorphism, we would expect that the Gln allele would be associated with higher susceptibility for all types of cancer." (PMID 24205095, 2013). "Similar to the results of our study, XRCC1 polymorphisms are also reported to be associated with some other cancers." (PMID 23496911, 2013). "The XRCC1 Arg399Gln polymorphism has been well studied in many cancers and positive correlations have been established; however, the results from these studies are not consistent." (PMID 23426866, 2013). "First, differently from previous meta-analyses, we explored the impact of XRCC1 Arg399Gln on a great diversity of cancer sites, allowing for a general view of its influence on cancer susceptibility." (PMID 24205095, 2013). "Although XRCC1-deficient cancer cell lines are viable, XRCC1-deficiency in mice is embryonically lethal." (PMID 23247283, 2012). "Three polymorphisms in XRCC1 (Arg194Trp, Arg280His and Arg399Gln) have been frequently examined in the studies on cancer susceptibility." (PMID 22984511, 2012). "A non-synonymous polymorphism in XRCC1, 399 G → A, has been shown to reduce effectiveness of such DNA repair and has been associated with the risk of certain cancers." (PMID 23101479, 2012). "The Arg194Trp, Arg280His, and Arg399Gln XRCC1 variants have been extensively studied in relation to cancer." (PMID 23247283, 2012). "Among XRCC1 polymorphisms, codon 399 polymorphism was well studied and was found to be associated with formation of several cancers, but the exact biochemical effect of the polymorphism is not fully characterized." (PMID 20431719, 2010). "A second XRCC1 polymorphism (Arg194Trp) has also been well studied, and most of the published codon 194 polymorphism studies reported a reduced risk of cancer associated with the Trp allele." (PMID 20431719, 2010). "The genes belonging to base excision repair (BER) pathway, such as X-ray Repair Cross Complementing Group 1 (XRCC1) have been extensively studied in the association with various human cancer." (PMID 19284666, 2009). "Some studies have assessed the association between XRCC1 gene polymorphisms and chemotherapy response in various carcinomas, but the results are inconsistent." (PMID 19563645, 2009).
cancer (continued). "Although there is an apparent divergence among the results, earlier studies have reported mainly the relationship between cancers and XRCC1-Arg399Gln and XPD-Lys751Gln polymorphisms." (PMID 17242676, 2007). "Studies of associations between the polymorphisms and cancer risk have been inconsistent, possibly because of linkage disequilibrium with a determinant variant of the XRCC1 gene." (PMID 16796765, 2006). "The variant carriers of XRCC1 codon 399 were not statistically significantly, but consistently, at decreased risk of cancer, whereas XRCC1 codon 280 heterozygotes were at increased risk of cancer." (PMID 16542436, 2006). "In conclusion, combined XPD and XRCC1 genotypes were shown to be associated with cancer-specific survival in muscle-invasive bladder cancer patients treated with CRT." (PMID 16880786, 2006). "Although there are many reports studying the association of both of these XRCC1 SNP in cancer, there have been relatively few studies of their functional significance." (PMID 17087834, 2006). "In multivariate analysis, only the combined XPD and XRCC1 genotypes were independently associated with cancer-specific survival (P=0.04)." (PMID 16880786, 2006). "Combined genotypes with at least one variant allele in XPD or XRCC1 were significantly associated with improved cancer-specific survival compared with remaining groups (P=0.009; log-rank test)." (PMID 16880786, 2006). "Combined genotypes with at least one variant allele in XPD or XRCC1 were significantly associated with improved cancer-specific survival compared with remaining groups (P=0.009)." (PMID 16880786, 2006). "A similar tendency of increased risk for advanced stage cancer was seen for subjects with the XRCC1-280 Arg/His or His/His genotype (OR 1.99, 95% CI 0.90–4.42) compared to subjects with the Arg/Arg genotype." (PMID 16280050, 2005). "Genetic variations in XRCC1 have been associated with an altered risk of developing cancer." (PMID 40722932, 2025). "Additionally, we investigated the potential association between XRCC1 genetic alterations and patient prognosis across different cancer types." (PMID 38217545, 2024). "The reduced DNA single-strand break repair and genomic instability caused by XRCC1 defects may contribute to cancer development." (PMID 38217545, 2024). "This suggests that mutations in XRCC1 are associated with cancer development and progression." (PMID 38217545, 2024). "Genetic polymorphisms in DNA repair genes such as XRCC1 may change the DNA repair capacity which subsequently has impacts on cancer susceptibility." (PMID 36573562, 2023). "While PARP1 inhibition, on the one hand, has been shown effective in inducing synthetic lethality in XRCC1-deficient sporadic cancers, XRCC1 protein levels, on the other hand, demonstrate correlation with cancer resistance to CPT treatment, which is reversible by PARP inhibition." (PMID 35778544, 2023). "As such, it is tempting to speculate that IDH1 mutant ALT cancers may exhibit high levels of trapped PARP1 through loss of XRCC1 protein activity." (PMID 36940725, 2023). "A meta-analysis of 38 case–control studies indicated that XRCC1 Arg194Trp may be a biomarker of cancer susceptibility." (PMID 35164849, 2022). "Similarly, a large number of germline and cancer-associated SNP variants that affect amino acid composition of XRCC1 have been reported in the human population, and epidemiology studies have found an association of some of these with cancer risk." (PMID 34339737, 2021). "Here we show that LIG1 blockade could be an attractive synthetic lethality strategy in XRCC1 deficient cancer cells." (PMID 34373746, 2021). "To evaluate whether LIG1 inhibition is synthetically lethal in XRCC1 deficient cells, we tested L82 in a panel of cancer cell lines." (PMID 34373746, 2021). "Finally, single-nucleotide polymorphisms (SNPs) of XRCC1 have been found as risk factors for the development of different types of cancer." (PMID 34339737, 2021).
cancer (continued). "For OS, the pooled HRs showed a strong correlation between high XRCC1 expression and poor OS, indicating that high XRCC1 expression could be considered a risk factor in cancer patients receiving radiotherapy." (PMID 34094945, 2021). "Therefore, both the conclusions about XRCC1 expression and cancer prognosis and the association between rs25487 and treatment response/side effects should be carefully assessed." (PMID 34094945, 2021). "For DNA ligase IIIα/XRCC1 interaction, when compared with wild-type XRCC1 (KD: 50.4 nM), the binding constant values for the cancer-associated variants P161L, R194W, R280H, R399Q, and Y576S showed similar interaction patterns as the KD values were in the range of 30 to 50 nM." (PMID 34339737, 2021). "Three main coding polymorphisms of XRCC1 at codon 194, codon 280, and codon 399 have been identified, which may affect DNA repair ability and subsequently cancer susceptibility." (PMID 34766149, 2021). "and master’s theses) on the association between XRCC1 expression level and radiotherapy-related treatment response/cancer prognosis; we also explored the relationship between XRCC1 rs25487 polymorphism and radiotherapy-related treatment response/radiation-induced side effects." (PMID 34094945, 2021). "Based on our results, XRCC1 polymorphism may be considered a substantial biomarker for cancer screening in high risk persons and for supporting these patients by prophylactic interventions and specific therapeutic methods." (PMID 32711416, 2020). "The reduced cancer risk found in our study, as well as other studies, was congruent with the hypothesis that the variant XRCC1 protein and its diminished DNA repair could enhance damage-related apoptosis in individual cells." (PMID 32212791, 2020). "Mutations of XRCC1 may increase the risk of cancer through impairing its interaction with other enzymatic proteins with consequent impairment of DNA repair activity." (PMID 32334466, 2020). "This conflicting role of XRCC1 polymorphisms indicates their risk effects may depend on cancer types and ethnic groups." (PMID 30362960, 2018). "XRCC1 polymorphisms are still a major topic in cancer research." (PMID 30408066, 2018). "XRCC1 gene polymorphisms are being increasingly explored in cancer epidemiology studies." (PMID 30362960, 2018). "Overall and subgroup analysis of the XRCC1 polymorphisms and cancer risk." (PMID 30408066, 2018). "The present meta-analysis suggests that as in other cancers, XRCC1 polymorphism may also influence tumorigenesis in the female reproductive system." (PMID 28415705, 2017). "Single nucleotide polymorphisms (SNPs) of XRCC1 gene acted as a risk factor might be a valuable genetic marker for chemotherapy in various cancers containing esophageal cancer." (PMID 25925371, 2015). "There is only one study from the CIMBA consortium which has evaluated the role of three of the most studied SNPs in the XRCC1 gene, c.-77C>T (rs3213245) p.Arg280His (rs25489) and p.Gln399Arg (rs25487), ruling out associations of these variants with cancer risk in BRCA1 and BRCA2 mutation carriers." (PMID 24698998, 2014). "The major significance of XRCC1 in maintaining genomic stability has been raised by high frequency of chromosome deletions or aberrations in the gene mutant cells, and thus the XRCC1 gene has been posed as a candidate gene for many cancer susceptibility." (PMID 24489692, 2014). "It has been demonstrated that XRCC1 polymorphisms could increase cancer risk by interacting with other gene polymorphisms in a multiplicative manner, such as adenosine diphosphate ribosyl transferase Val762Ala and XRCC1 Arg399Gln polymorphisms." (PMID 23704969, 2013). "Interestingly, the data of meta-analysis revealed the protective effect of the XRCC1 194Trp allele for tobacco-related types of cancer, which was compatible with the evidence of lower mutagen sensitivity for this allele." (PMID 23675381, 2013).
cancer (continued). "Therefore, we performed a comprehensive meta-analysis by including the most recent and relevant articles to identify statistical evidence of the association between XRCC1 Arg399Gln polymorphism and risk of all cancers that have been investigated." (PMID 24205095, 2013). "And this indicates that it may be not appropriate to use an overall estimation of the relationship between XRCC1 Arg399Gln polymorphism and risk of cancer." (PMID 24205095, 2013). "A total of 895 articles regarding XRCC1 polymorphisms with respect to cancer were identified." (PMID 24205095, 2013). "The presence of the variant 399Gln in XRCC1 has been shown to be associated with higher levels of DNA adducts and higher sister chromatid exchange frequencies as well as measurable reduced DNA repair capacity and increased risk of several types of cancers." (PMID 24053728, 2013). "In order to resolve this conflict, the meta-analysis of 297 eligible studies including 93,941 cases and 121,480 controls was performed to derive a more precise estimation of the association between XRCC1 Arg399Gln polymorphism and risk of different types of cancer." (PMID 24205095, 2013). "This mutation could alter XRCC1 function, diminish repair kinetics, and influence susceptibility to adverse health effect, such as cancer." (PMID 24205020, 2013). "In human association studies, germline polymorphisms in XRCC1 may influence cancer risk and influence response to platinum based chemotherapy." (PMID 23451157, 2013). "The explanation for the results may be that functional variants in the XRCC1 gene may play a crucial role in the facilitation of human cancer development because of the alteration of BER functions." (PMID 22984511, 2012). "However, more data regarding XRCC1 and cancer susceptibility is published weekly, and in a recent meta-analysis the Arg399Gln variant was found to be associated with increased risk of developing breast cancer." (PMID 23247283, 2012). "Mutations of XRCC1 may increase the risk of cancers by impairing the interaction of XRCC1 with other enzymatic proteins and consequently altering DNA repair activity." (PMID 22984511, 2012). "Previous reports have indicated that the X-ray repair cross-complementing gene 1 (XRCC1) Arg194Trp polymorphism may be a risk factor for several types of cancer." (PMID 23226774, 2012). "Therefore, the amino acid substitutions in codon 399 are proposed to change the function of the protein, and the 399Gln allele of XRCC1 has an important and potentially harmful phenotype and is reported to be associated with cancer." (PMID 20431719, 2010). "Few studies have investigated the association between the XRCC1 280His allele and risk of cancer." (PMID 16542436, 2006). "This could enable XRCC1 to accelerate a crucial repair step, which is especially important in a case when the polβ DNA synthesis activity is limiting in the cell as reported for many cancer-associated polβ variants." (PMID 34339737, 2021). "In addition, XRCC1 gene polymorphisms are closely related to radiotherapy in various cancers." (PMID 34766149, 2021). "The XRCC1 SNPs rs25487, rs1799782, and rs25489 have been linked to susceptibility for several types of cancer, but it is unclear whether this is also true for female reproductive system cancer." (PMID 28415705, 2017). "Interestingly, this motif in XRCC1 harbours a common polymorphism at amino acid 399 (arginine/glutamine), which in some epidemiological studies has been implicated in altered predisposition to cancer." (PMID 26130715, 2015). "Many studies have reported the association of XRCC1 Arg399Gln polymorphism with risk of cancer, however, the results remained controversial, although some original studies thought that Arg399Gln polymorphism was associated with risk of cancer, others had different opinions." (PMID 24205095, 2013).